TXNRD1 (thioredoxin reductase 1)
Diseases named in the same sentence as TXNRD1 in open-access papers (continued):
Sharing a sentence is not in itself a finding about the gene and the disease.
hepatocellular carcinoma (28 papers, 2016 to 2025). A malignant tumor that arises from hepatocytes. "Recently, TXNRD1 was found to be a risk factor for patients with hepatocellular carcinoma." (PMID 29910195, 2018). "However, another study demonstrated that expression of miRNA‐125b‐5p is correlated with a poor prognosis in hepatocellular carcinoma patients by targeting thioredoxin‐1 (TXNRD1), a key molecule associated with intracellular redox homeostasis that promotes energy and carbohydrate metabolism." (PMID 32592277, 2020). "Selenium-containing antioxidant enzymes such as glutathione peroxidase 4 (GPx4) and thioredoxin reductase 1 (TrxR1, encoded by TXNRD1) have emerged as therapeutic targets in hepatocellular carcinoma (HCC), a highly treatment-resistant cancer." (PMID 40818321, 2025). "Multifactorial Cox regression of 11 prognostic genes resulted in seven independent risk genes affecting the prognosis of patients with hepatocellular carcinoma, namely ENO1, NDRG1, NPM1, H2AX, IL33, MT3 and TXNRD1." (PMID 38097352, 2023). "miR-125-5p was detected earlier in the circulating EVs of HCV-induced liver cancer and miR125b-5p inhibiting TXNRD1 acting as a tumor suppressor in hepatocellular carcinoma." (PMID 37762298, 2023). "Thioredoxin reductase 1 (TXNRD1) is a member of the thioredoxin system, regulating hepatocellular carcinoma, epilepsy, osteosarcoma." (PMID 37621558, 2023). "We also found that the expression of NDRG1, NPM1, TXNRD1 in the hepatocellular carcinoma samples from patients with poor prognosis were higher than the samples from patients with better prognosis." (PMID 38097352, 2023). "Compared with the paracellular tissues, the expression of NDRG1, NPM1, TXNRD1 were both increased in the hepatocellular carcinoma samples." (PMID 38097352, 2023). "In summary, we provide novel evidence that USF2-mediated upregulation of TXNRD1 contributes to hepatocellular carcinoma progression by activating Akt/mTOR signaling." (PMID 36319631, 2022). "Consistent with our findings, TXNRD1 was found to play a decisive role in hepatocellular carcinoma malignancy." (PMID 35814476, 2022). "The TXNRD1 was a vital ferroptosis-related gene and has been approved to promote the invasion, progression, and metastasis of hepatocellular carcinoma." (PMID 35401932, 2022). "In conclusion, our findings reveal that USF2-mediated upregulation of TXNRD1 contributes to hepatocellular carcinoma progression by activating Akt/mTOR signaling." (PMID 36319631, 2022). "Suppression of TXNRD1 inhibited the proliferation and induced apoptosis of hepatocellular carcinoma cells by modulating redox balance in vitro." (PMID 35127477, 2021). "Another identified target of miR‐125b in regulating hepatocellular carcinoma metastasis is thioredoxin reductase 1 (TXNRD1), a regulator of endocellular oxidative stress and a promoter of tumour development." (PMID 33332677, 2021). "As described in some hepatocellular carcinoma cases, TXNRD1 was elevated to control the ROS level and maintain the tumorigenesis." (PMID 33292234, 2020). "Immunoblotting results revealed higher expression of PCK1 and lower expression of TXNRD1 in tumor tissues derived from the PCK1-overexpressing hepatoma cells than in GFP control group." (PMID 30619751, 2018). "TXNRD1 is upregulated in many human malignancies, and inhibition of the TXN pathway causes hepatoma cell death." (PMID 30619751, 2018). "TXNRD1 was widely reported to participate in the positive regulation of hepatocellular carcinoma." (PMID 33292234, 2020). "Together, these results suggested that PCK1 could inhibit hepatoma cell growth in vivo by decreasing ROS level and TXNRD1 expression." (PMID 30619751, 2018). "Thioredoxin reductase 1 (TXNRD1) is an antioxidant enzyme reportedly overexpressed in hepatocellular carcinoma (HCC); however, the detailed function and mechanisms of TXNRD1 in HCC remain obscure." (PMID 31384178, 2019).
hepatocellular carcinoma (continued). "In line herewith, we observed that TXNRD1 may be related to drug resistance of hepatoma cells." (PMID 30619751, 2018). "Finally, we found that auranofin, a TXNRD1 inhibitor, enhanced the sensitivity of PCK1-knockout hepatoma cells to sorafenib-induced apoptosis." (PMID 30619751, 2018).
liver cancer (16 papers, 2013 to 2025). An epithelial or non-epithelial malignant neoplasm that arises from the liver. "TXNRD1-deficient mice exposed to a liver carcinogen showed a significantly increased incidence for chemically induced liver cancer." (PMID 36319631, 2022). "TXNRD1 was reported to function in regulating the ferroptosis of liver cancer and chronic myeloid leukemia cells." (PMID 37834393, 2023). "The tumors from the three liver cancer patients also manifested a significantly higher increase in TXNRD1 levels." (PMID 26569310, 2015). "Acetyl CoA synthase is necessary for acetate-dependent lipid synthesis in liver cancer cells; thioredoxin reductase 1 expression is enhanced by particular phospholipids of oxidized LDLs, and oxLDL also upregulates Tribbles3 and p21 expression." (PMID 24039668, 2013). "TXNRD1 was proposed as a biomarker to monitor therapeutic efficacy for liver cancer." (PMID 36839749, 2023). "Our finding provides new insights into the mechanism of antioxidant enzyme gene TXNRD1 mediated by altered metabolism in liver cancer, and might offers a potential therapy for HCC." (PMID 30619751, 2018). "LASSO Cox regression analysis showed that the four genes had the highest predictive value for OS in liver cancer, and according to lambda, using the following formula to establish a prognostic signature: Risk score = (0.075 × DLAT + 0.223 × GSR + 0.091 × RPE + 0.068 × TXNRD1)." (PMID 37828099, 2023). "We experimentally confirmed that p62 depletion in liver cancer cell lines downregulates the expression of SRX1 and TXNRD1 at both transcriptional and translational levels, and reduces cell proliferation." (PMID 35814476, 2022). "The amounts of three key proteins in the TXN system, TXNRD1, TXN, and peroxiredoxin 1 (PRDX1), in tumor and surrounding normal tissue samples from the three lung and three liver cancer patients were examined in duplicate by western blotting." (PMID 26569310, 2015). "Importantly, we experimentally validated that p62 depletion in liver cancer cell lines downregulates the expression of SRX1 and TXNRD1 at both transcriptional and translational levels, and reduces cell proliferation." (PMID 35814476, 2022).
melanoma (16 papers, 2013 to 2025). A malignant, usually aggressive tumor composed of atypical, neoplastic melanocytes. "Previous studies have shown that both X-linked inhibitor of apoptosis (XIAP) and thioredoxin reductase 1 (TrxR1) participate in the resistance of melanoma to chemotherapy-induced cell death." (PMID 40486906, 2025). "The results of the present study demonstrated that under hypoxic conditions the inhibition of WM115 and WM266-4 melanoma cell proliferation is associated with decreased thioredoxin reductase 1 on both mRNA and protein levels." (PMID 37892173, 2023). "It was shown that, under hypoxic conditions the inhibition of WM115 and WM266-4 melanoma cell proliferation was associated with decreased expression of thioredoxin reductase-1 and cystathionine β-synthase." (PMID 37892173, 2023). "We see a more dramatic effect on the expression of melanin synthesis enzymes in M14 melanoma cells in which we have disrupted the gene encoding TXNRD1 using Crispr/Cas9." (PMID 36291795, 2022). "As a transcriptional target of NRF2, thioredoxin reductase 1 (TR1) is important for sustaining the antioxidant capacity of melanoma cells." (PMID 40617808, 2025). "They showed that the activity of miR-21-3p on TXNRD1 was able to generate ferroptosis in melanoma by enhancing lipid peroxidation." (PMID 41339932, 2025). "Among them, TXNRD1 is targeted by arsenic trioxide and fotemustine (approved in some countries against melanoma brain metastasis), and RRM1-2 by seven antimetabolites." (PMID 38701414, 2024). "Under the hypoxic condition, the expression of mRNA and the protein level of thioredoxin reductase-1 were significantly reduced in both melanoma WM115 as well as in WM266-4 cells after 24 h of culture in a low oxygen environment." (PMID 37892173, 2023). "So, it would be interesting to determine the effect that combinatorial inhibition of MAPK signaling and thioredoxin reductase 1 would have on melanoma cells." (PMID 35326683, 2022). "Taken together, miR-21–3p directly targeted TXNRD1 to promote lipid peroxidation generation and ferroptosis in melanoma." (PMID 35738798, 2022). "Melanoma cells in which the TR1 gene (TXNRD1) was disrupted using Crispr/Cas9 showed more dramatic effects including the complete loss of the melanocyte-specific isoform of MITF; other MITF isoforms were unaffected." (PMID 36291795, 2022). "We then employed TXNRD1 inhibitor Auranofin to treat melanoma cells co-treated with antagomiR-21–3p and then underwent erastin or RSL3 stimulation." (PMID 35738798, 2022). "We also examined the transcription of melanin synthesis genes TYR, TYRP1, PMEL, MLANA and DCT by RNAseq analysis in M14 human melanoma cells in which we have disrupted TXNRD1 using Crispr/Cas9 (M14TXNRD1+/− cells)." (PMID 36291795, 2022). "A recent report demonstrated that MITF regulates the expression of SOX10, and our RNAseq data shows that SOX10 is also significantly depleted in the TXNRD1+/− melanoma cells (less than 1% that of the TXNRD1wt cells, padj = 1.2 × 10−10)." (PMID 36291795, 2022). "The inhibition of TXNRD1 activity by Auranofin abolished the protective effect of antagomiR-21–3p on erastin or RSL3-triggered ferroptosis in melanoma cells as revealed by CCK8 and colony formation assays." (PMID 35738798, 2022). "We saw a similar effect when we silenced TXNRD1 using a mixture of three siRNAs in the M14 melanoma cell line." (PMID 36291795, 2022). "The study demonstrated that TXNRD1 was a novel direct target of miR-21–3p in human melanoma cells." (PMID 41339932, 2025).
melanoma (continued). "In that same study, it was also demonstrated that the knockdown of TXNRD1 induces glycolysis dependency in melanoma cell lines, and that the combination of TXNRD1 knockdown with a pharmacological blockade of glycolysis-hindered metastasis in a mouse xenograft model." (PMID 35326683, 2022). "MITF-M, in cooperation with Lef1, also regulates its own gene transcription in M14 cells, and this, in turn, could result in differential regulation of gene expression downstream of MITF-M that we observe in the TXNRD1+/− melanoma cells." (PMID 36291795, 2022). "The expression of both TXN and TXNRD1 is known to be elevated in melanomas and other cancers." (PMID 35326683, 2022). "First, we found that treatment of patient-derived melanoma CTCs with hydrogen peroxide (H2O2) (0–25 μM)—a major component of ROS—caused a dose-dependent increase of NRF2 target gene expression along with downstream anti-oxidant CAT, GSS, and TXNRD1 effector genes." (PMID 31003475, 2019). "Thus, both CBS and TXNRD1 may also be important therapeutic targets in the treatment of melanoma." (PMID 37892173, 2023). "Hypoxia reduces the expression (mRNA/protein level) of cystathionine beta-synthase as well as thioredoxin reductase 1 and inhibits the proliferation of WM115 and WM266-4 melanoma cells." (PMID 37892173, 2023). "Our previous investigations proved that miR-21-3p and CAMKK2 regulated the TXNRD1 and AMPK-Nrf2 axes, respectively, to mediate the execution of melanoma cell ferroptosis." (PMID 36429010, 2022). "Here, we demonstrate that the antioxidant enzyme thioredoxin reductase-1 controls the stability and function of MITF, the master regulator of melanocytes and melanoma." (PMID 36291795, 2022). "Consistent with previous reports that associated the Nrf2 pathway with SFN-induced chemoprevention, we found that the Nrf2 target genes HMOX1, TXNRD1, GCLC, GCLM, AKR1B10 and G6PD were upregulated after melanoma treatment." (PMID 28864908, 2018). "Based on our results, we can say that in melanoma cell lines such as WM115 and WM266-4 cells, the downregulation of CBS, as well as thioredoxin reductase 1 expression, may play a significant role in inhibiting cell proliferation." (PMID 37892173, 2023). "The knockdown of thioredoxin reductase 1 alone in melanoma alone does not prevent metastasis but does induce a dependency on glycolysis, and a complete knockout of TXNRD1 in melanocytes increases the nuclear localization of NRF2 and the synthesis of GSH post-UVB irradiation." (PMID 35326683, 2022). "Some studies have demonstrated the upstream regulatory mechanism of ferroptosis in melanoma before, and we previously reported that CAMKK2 and miR-21-3p were critical regulators of melanoma cell ferroptosis through the regulation of AMPK-Nrf2 and TXNRD1, respectively." (PMID 36429010, 2022).
non-small cell lung carcinoma (16 papers, 2010 to 2025). A group of at least three distinct histological types of lung cancer, including non-small cell squamous cell carcinoma, adenocarcinoma, and large cell carcinoma. "TXNRD1 was a significant predictor of poor treatment outcome in non-small cell lung cancer and was correlated with shorter disease-free survival." (PMID 36839749, 2023). "In non-small cell lung carcinoma (NSCLC) models, dual treatment with the thioredoxin reductase-1 (TXNRD1) antioxidant inhibitor auranofin and MK2206 induced cancer cell-specific apoptosis through ROS-stimulated JNK signaling." (PMID 29868481, 2018). "In non-small cell lung cancer (NSCLC), TXNRD1 overexpression, driven by NRF2 signaling, has been associated with tumor recurrence, adverse clinical outcomes, and chemoresistance, ultimately enhancing cancer cell survival." (PMID 41333220, 2025). "In non-small cell lung cancer (NSCLC) H1299 cells, PK11007-induced TXNRD1 inhibition disrupted cellular redox balance, leading to impaired autophagy flux and cell death." (PMID 41154531, 2025). "We challenged a panel of 31 non-small cell lung cancer (NSCLC) cell lines with a novel, potent and selective inhibitor of thioredoxin reductase 1 (TXNRD1), recently developed by our group, for its central role in redox regulation." (PMID 36958250, 2023).
gastric cancer (15 papers, 2014 to 2025). A primary or metastatic malignant neoplasm involving the stomach. "The loss of activity in TXNRD1 led to ROS-dependent cell death, which supports a redox-targeting strategy in the chemotherapy of gastric cancer." (PMID 37836684, 2023). "Additionally, high expression of TXNRD1 is significantly associated with poor outcomes in patients with gastric cancer." (PMID 37836684, 2023). "TXN and TXNRD1 expression levels significantly increased in tumor tissue samples from colorectal, lung, and stomach cancers." (PMID 39744566, 2025). "In this study, the inhibition of three benzophenanthridine alkaloids, including chelerythrine, sanguinarine, and nitidine, on recombinant TXNRD1 was investigated, and their anti-cancer mechanisms were revealed using three gastric cancer cell lines." (PMID 37836684, 2023). "Taken together, this study demonstrates that chelerythrine is a novel inhibitor of TXNRD1 by targeting Sec498 and possessing high anti-tumor properties on multiple gastric cancer cell lines by eliciting necroptosis." (PMID 37836684, 2023). "Here, we showed that two natural compounds, chelerythrine and sanguinarine, suppress the growth of gastric cancer cells by inhibiting TXNRD1 and inducing oxidative stress in NCI-N87 cells." (PMID 37836684, 2023). "It has been found that PL induced SGC-7901 and BGC-823 gastric cancer cells growth inhibition by suppressing the activity of thioredoxin reductase 1 enzyme (TrxR1) which regulates cellular redox balances and is a major line of cellular defense against ROS." (PMID 33167519, 2020). "Recent studies have revealed that targeting TXNRD1 with small molecules is a viable approach to achieving therapeutic activity and selectivity, indicating the anti-cancer potential of inhibiting TXNRD1 in gastric cancer." (PMID 37836684, 2023). "Compared to normal tissues, TXNRD1 was up-regulated in gastric tumors, suggesting that TXNRD1 could be a potential cellular target for the treatment of gastric cancers." (PMID 37836684, 2023). "Similarly, an allylated MAC inhibited gastric cancer growth by increasing ROS through directly binding to and inhibiting TXNRD1, which in turn activated FoxO3a through suppressing Akt." (PMID 36319631, 2022). "We report here that EF24 may interact with the thioredoxin reductase 1 (TrxR1), an important selenocysteine (Sec)-containing antioxidant enzyme, to induce reactive oxygen species (ROS)-mediated apoptosis in human gastric cancer cells." (PMID 26919110, 2016). "In our opinion, TXNRD1 may participate in the suppression of gastric cancer genesis or the up-regulation of TXNRD1 may be an adaptive mechanism in response to oxidative stress generated by overexpression of NAIF1." (PMID 24926661, 2014). "Recent pioneers demonstrated that chaetocin inhibited TXNRD1 and subsequently induced excessive ROS accumulation followed by inactivation of the PI3K/AKT pathway in gastric cancer cells." (PMID 36319631, 2022). "There have been no studies to investigate the role of TXNRD1 in gastric cancer." (PMID 24926661, 2014).
colon cancer (14 papers, 2010 to 2025). "The adjusted risk for SelN1 and colon cancer and both TXNRD1 SNPs and rectal cancer remained statistically significant after adjustment for multiple comparisons." (PMID 22615972, 2012). "TXNRD1, TXNRD2, TXNRD3, and SelN1 interacted with BMI to alter risk of colon cancer and TXNRD1 interacted with BMI to statistically alter risk associated with rectal cancer." (PMID 22615972, 2012). "TXNRD1, TXNRD3, SeP15, and SepX1 were associated with survival after colon cancer diagnosis; SeP15 and SepX1 remained significant after FDR multiple comparison adjustment (HRR 1.47, 95% CI 1.13,1.90 and HRR 1.47 95% CI 1.3,1.90 respectively)." (PMID 22615972, 2012). "Interactions between aspirin/NSAIDs with TXNRD1 rs4964778 remained statistically significant for colon cancer after adjustment for multiple comparison; rs17745445 of TNXRD2 was borderline significant after adjustment for multiple comparison with the step-down Bonferroni correction." (PMID 22615972, 2012). "Two SNPs in TXNRD1 and four SNPs in TXNRD2 interacted with aspirin/NSAID to influence colon cancer; one SNP in TXNRD1, two SNPs in TXNRD2, and one SNP in TXNRD3 interacted with aspirin/NSAIDs to influence rectal cancer." (PMID 22615972, 2012). "Although three SNPs in TXNRD1, TXNRD2 and SelN1 were associated with colon cancer, none remained statistically significant after adjustment for multiple comparisons as indicated by the pACT." (PMID 22615972, 2012).